RET (ret proto-oncogene)
Diseases named in the same sentence as RET in open-access papers (continued):
Sharing a sentence is not in itself a finding about the gene and the disease.
cancer (continued). "Other MKIs have been studied in RET-altered cancers including lenvatinib, which had modest success in MTC with ORR 36% and PFS of 9 months." (PMID 39655713, 2025). "In RET-fusion-positive cancers, BET inhibitors (e.g., JQ1) disrupt BRD4-mediated transcriptional elongation of RET, potentiating the effects of RET TKIs." (PMID 40599544, 2025). "RET is a validated drug target, and several RET inhibitors (e.g., Selpercatinib or Pralsetinib) have been approved or are in development for RET‐driven cancers." (PMID 39825568, 2025). "Selpercatinib and pralsetinib, two of these agents, have shown significant clinical promise and received approval from the U.S. Food and Drug Administration (FDA) in 2020 for treating RET-altered cancers." (PMID 41465145, 2025). "LIBRETTO-001 is an open-label phase I/II, single-arm study of selpercatinib in RET-dependent cancers; the 2025 final analysis reports efficacy and safety in RET-fusion-positive NSCLC." (PMID 41154602, 2025). "Cabozantinib has also been studied in other RET-altered cancers including renal cell carcinoma and NSCLC." (PMID 39655713, 2025). "It specifically targets the abnormal RET protein, blocking its activity and thereby inhibiting cancer cell growth." (PMID 40141188, 2025). "It received further FDA approval for its utilization in unresectable or metastatic RET-positive cancers, locally advanced or metastatic solid tumors in patients ≥ 12 years old, in September 2022." (PMID 41179283, 2025). "Somatic or germline RET alterations are druggable targets, which enables personalised cancer treatments." (PMID 40138217, 2025). "According to COSMIC, 25% of recurring fusions are RTK oncofusions such as EML4::ALK and CCDC6::RET which have been extensively studied as drivers of many different cancer types." (PMID 38833619, 2025). "Basket trials have shown the efficacy of therapies targeting fusion drivers across solid tumors, leading to pan-cancer approvals for RET and NTRK1/2/3 fusions." (PMID 41091579, 2025). "The application of RET inhibitors in treating these cancers has evolved significantly, with a focus on developing selective inhibitors to improve efficacy and reduce side effects." (PMID 39925808, 2025). "ALK-rearranged carcinomas are less frequent than those with RET or NTRK rearrangements, and typically involve fusion with partner genes, such as STRN (encoding striatin) or EML4 (also involved in lung adenocarcinoma)." (PMID 41175860, 2025). "RET-rearranged carcinomas are typically aggressive at presentation, but generally have a favorable prognosis, as they tend to respond to radioactive iodine therapy." (PMID 41175860, 2025). "Dysregulation of RTKs, notably the rearranged during transfection (RET) kinase, contributes to tumorigenesis in various cancers." (PMID 39086985, 2024). "RET inhibitors work by targeting the RET protein or disrupting downstream signaling pathways to prevent cancer cells from growing and dividing uncontrollably." (PMID 38501105, 2024). "In cancers where RET fusions are rare, such as NSCLC, next-generation sequencing (NGS) with broad panel assays are recommended to allow for screening in a histotype-agnostic manner." (PMID 39199650, 2024). "By inhibiting RET, selpercatinib helps to disrupt the signaling pathways that promote cancer growth and survival in cells where RET alterations are present." (PMID 39882443, 2024). "Our results are consistent with the effects of RET in promoting cancer cell proliferation and invasion, as patients with high RET expression demonstrated shorter PFS." (PMID 38738791, 2024). "As more patients with RET-altered cancers are tested and identified in the real world, studies with a larger sample size are needed to confirm our findings, as well as CNS outcomes related to the real-world use of selpercatinib." (PMID 39594790, 2024). "The majority of the patients (n = 31) had GI RET-positive cancers, with pancreatic and colorectal being the most common." (PMID 39518080, 2024).
cancer (continued). "Predictions for patients with other RET fusion-positive/RET-altered cancers were similar between the parametric and ML methods and is characterized by wider prediction intervals, partly reflecting the small number of patients in these groups." (PMID 38919267, 2024). "The RET gene is also a therapeutic target for RET-driven malignant tumors, and targeted therapy is an important treatment method for advanced MTC with RET gene point mutations." (PMID 40017634, 2024). "Overall, this case report highlights the potential of FDG-PET/CT as a valuable tool for response assessment in RET positive cancers treated with selpercatinib." (PMID 39272672, 2024). "The findings suggest that FDG-PET has the potential to serve as a non-invasive biomarker for monitoring treatment response in patients with RET-positive cancers." (PMID 39272672, 2024). "Discussion: The identification of RET SSVs in all MTCs, but rarely in other cancer types, demonstrates that these RET SSVs distinguish MTCs from other cancer types." (PMID 38566816, 2024). "RET is reported to participate in the development of malignant tumors by activating the AKT/mTOR signaling." (PMID 37874339, 2024). "This case report marks the first instance of a patient diagnosed with RET aberrant cancer exhibiting both NTRK and ALK fusions, who underwent treatment with an NTRK inhibitor and subsequently with an NTRK/ALK inhibitor." (PMID 38438731, 2024). "The discovery of RET fusions across a spectrum of cancers has underscored their role as actionable targets for kinase inhibitor therapy, with their presence often indicating sensitivity to specific RET inhibitors." (PMID 38539256, 2024). "The presence of residual tumors in most patients with RET-altered cancer after selpercatinib or pralsetinib treatment requires long-term disease management." (PMID 38438731, 2024). "Currently, more and more inhibitors targeting RET variation are used in the treatment of human cancers." (PMID 38734621, 2024). "Oncogenic RET alteration is an important, tissue-agnostic therapeutic target across diverse cancers." (PMID 39489747, 2024). "NTRK and RET fusions are found in less than 5% of the population, with predominance in rare cancers." (PMID 39518080, 2024). "Rearranged during transfection (RET) rearrangement oncoprotein-mediated Ras/MAPK signaling cascade is constitutively activated in cancers." (PMID 38805286, 2024). "The RET/PTC inhibitor LOXO292 (selpercatinib) has been approved by the US Food and Drug Administration to treat RET-altered cancers, including advanced thyroid cancer harboring RET/PTC, with good therapeutic responses in some patients but not in others." (PMID 38735658, 2024). "More recently, selective RET inhibitors showed remarkable activity in multiple cancer types sharing RET rearrangements." (PMID 39211557, 2024). "For example, the RET inhibitor selpercatinib is approved for cancers harboring a RET gene fusion, which was identified in 0.6% (1/160) of PDAC cases in one study." (PMID 38398185, 2024). "Given the key role of the RET oncogene in cancer, its inhibition has represented an attractive therapeutic strategy." (PMID 39211557, 2024). "Preliminary insights gleaned from three cases hint at the potential of 18FDG PET/CT as a tool for evaluating disease control and metabolic response in RET-positive cancers." (PMID 39272672, 2024). "For example, selpercatinib, a selective RET inhibitor designed to inhibit diverse RET fusions, was used in the thyroid, lung, and other cancers." (PMID 38734621, 2024). "FDG-PET has been established as a reliable surrogate marker for response in various oncogene-driven cancers, although limited data exists for its use in RET-positive cancers." (PMID 39272672, 2024). "All five genes (BAP1, FANCA, RET, FH, and RAD51C) are well-known cancer predisposing genes with incomplete penetrance and variability of expression." (PMID 38700789, 2024).
cancer (continued). "The mutation frequencies in BRAF, TERT, RET, ATM and GGT1 were significantly higher in cancer tissues than benign nodules." (PMID 38886866, 2024). "RET can also act as an oncogene and participate in the development and progression of several human cancers." (PMID 38532419, 2024). "Whereas RET-selective protein tyrosine kinase inhibitors selpercatinib and pralsetinib rendered high rates of responses in RET-altered cancers, less than 10% of patients achieved a complete response." (PMID 38438731, 2024). "Early studies have shown that changes in FDG uptake on PET scans correlate with treatment response in RET-positive cancers treated with multi-kinase inhibitors that have RET activity like lenvatinib or cabozantinib or vandetanib." (PMID 39272672, 2024). "The paper includes insightful case studies that highlight the successful application of RET inhibitors in the treatment of RET-positive cancers." (PMID 39272672, 2024). "This case not only underscores the efficacy of selpercatinib in treating RET fusion-positive rare tumors but also highlights the potential of wearable technology in cancer care." (PMID 39085487, 2024). "The introduction of selective RET inhibitors has truly transformed the management of RET-positive cancers, offering a targeted and effective treatment option for patients with these specific molecular alterations." (PMID 39272672, 2024). "Here, we report 9 out of 24 patients with non-contributory family history, harboring germline heterozygous deleterious mutation in well-known cancer predisposing genes (CHEK2, RAD51C, BRCA2, FANCA, RET, FH, and BAP1)." (PMID 38700789, 2024). "Recently, the European Medicines Agency (EMA) granted approval for selpercatinib in RET-fusion-positive cancers." (PMID 39085487, 2024). "These inhibitors have been specifically designed to target and inhibit the abnormal activity of RET proteins in cancer cells, offering a promising avenue for treatment." (PMID 39272672, 2024). "RET is also a membrane protein that is expressed at significantly lower levels in cancer tissues than in normal tissues (P < 0.0001)." (PMID 38532419, 2024). "Dysregulation of RET contributes to cancer development, highlighting the importance of identifying lead compounds targeting this protein due to its pivotal role in cancer progression." (PMID 39086985, 2024). "Since the fusion was identified, she has been receiving treatment with selpercatinib, which was approved by the U.S. Food and Drug Administration for treatment of any cancer with RET fusion/gene rearrangement." (PMID 39410042, 2024). "Genomic alterations in RET can abnormally activate the unregulated oncogenic signaling that triggers cell growth and subsequent RET-activated cancers." (PMID 39594790, 2024). "The results must be interpreted with caution given the wide 95% CIs resulting from the limited sample size, which reflects the rarity of RET-altered cancers." (PMID 39594790, 2024). "In this work, we explore the efficacy of selective RET inhibitors targeting RET-positive cancers, employing FDG uptake analysis as our primary investigative tool." (PMID 39272672, 2024). "This discrepancy prompted further investigation into the use of FDG-PET as a potential surrogate marker for response assessment in RET-positive cancers." (PMID 39272672, 2024). "When RET becomes abnormally activated or fused with other genes, it can drive the development and progression of several types of cancers." (PMID 39272672, 2024). "This work explores the effectiveness of selective RET inhibitors in targeting RET-positive cancers and investigates the utility of FDG-PET in assessing treatment response." (PMID 39272672, 2024). "In vivo, selpercatinib has been shown to inhibit the growth of RET-altered human cancer cell lines and patient-derived xenografts, including a patient-derived RET fusion + xenograft injected orthotopically into the brain." (PMID 39199650, 2024).
cancer (continued). "Selective RET inhibitors, such as selpercatinib and pralsetinib, have revolutionized the treatment of cancers with RET gene alterations." (PMID 39272672, 2024). "Various RET gene alterations have been identified as key drivers in the growth and proliferation of cancer cells." (PMID 38791529, 2024). "For patients with RET fusion-positive cancers, brain metastasis is common and responses to multikinase inhibitors are often suboptimal." (PMID 39594790, 2024). "Among these breakthrough treatments, the emergence of selective RET inhibitors, such as selpercatinib and pralsetinib, has revolutionized the therapeutic landscape for cancers characterized by RET gene alterations." (PMID 39272672, 2024). "Targeting RET has shown significant success, particularly in cancers characterized by specific genetic alterations involving the RET kinase." (PMID 39086985, 2024). "We found that a small number of genes (e.g., RET, RECQL4, CUX1, FGFR4, PIK3R1, FGFR3, and GNAS) had some co-occurring variants per patient in different cancer types." (PMID 38637555, 2024). "A recent update in the ongoing study includes more patients (n = 52) and 16 months longer follow-up being treated with selpercatinib for RET-activated cancers." (PMID 39518080, 2024). "DNA/RNA-based NGS, in particular, has become a cornerstone in the identification of RET fusions, allowing for the comprehensive profiling of cancer genomes and the detection of fusions across a wide range of known and novel partner genes." (PMID 38539256, 2024). "Generally, the level of knowledge with regard to the lichen-related mechanisms that are connected to the RET proto-oncogene or to the endocrine panel of tumors/cancers remains a matter of debate and further studies are mandatory." (PMID 39585007, 2024). "New selective RET inhibitors (e.g., selpercatinib or pralsetinib) have revolutionized the treatment of cancer and have been approved as a treatment option for cancers with RET gene alterations." (PMID 39595993, 2024). "The use of selective RET inhibitors offers several advantages for the treatment of RET-positive cancers." (PMID 39272672, 2024). "All ALK and ROS1 fusions were detected in adenocarcinomas, and RET fusions were detected mostly in adenocarcinomas (11/12, 91.7%), except in one case of poorly differentiated carcinoma." (PMID 39507756, 2024). "Alterations in the RET gene have been described in different cancer types and can lead to uncontrolled activation of multiple proliferative signaling pathways." (PMID 38118420, 2023). "While it is currently being investigated in clinical trials, Selpercatinib obtained accelerated approval from the FDA in 2020 for the treatment of specific RET-driven cancers." (PMID 37375228, 2023). "More recently, selpercatinib has received accelerated US Food and Drug Administration (FDA) approval for RET-fusion-positive cancers in a tissue-agnostic indication." (PMID 38118420, 2023). "RET functions as an oncogenic driver in a variety of cancers and serves as a therapeutic target, with selective RET inhibitors showing promising results in patients." (PMID 36437415, 2023). "We then assessed the association of SYK with the therapeutic response to c-Metis, EGFRis, and other kinase inhibitors for the treatment of NSCLC, such as ALKis and RET inhibitors (RETis), in 15 cancer cell lines." (PMID 37183231, 2023). "The LIBRETTO-001 trial enrolled patients with RET-activated cancers treated with selpercatinib in various lines of therapy." (PMID 38201566, 2023). "Inhibition of RET-fused cancers is achieved by competing with ATP, leading to a reduction in the colony-forming ability of RET-fused cell lines." (PMID 37375228, 2023). "In 2022, selpercatinib received full FDA approval for NSCLC and accelerated approval in a tissue-agnostic manner for all cancers harboring RET fusions." (PMID 38118420, 2023).
cancer (continued). "Since the ddPCR system established in this study provided a sensitive method for CCDC6::RET fusion detection, application of this method to these cancer types would be benefits more RET fusion-positive patients in the clinic." (PMID 37081420, 2023). "Alterations in the Rearranged during Transfection (RET) receptor are frequently found in several types of cancers." (PMID 38201566, 2023). "On a larger scale, much-needed efforts are underway to better coordinate medical systems, manufacturers, and regulators nationally and internationally to improve care for patients with RET-altered cancers." (PMID 37277734, 2023). "A phase I/II clinical trial (NCT04161391) is ongoing to evaluate the efficacy and safety of TPX-0046 in advanced cancers harboring RET mutants." (PMID 36865807, 2023). "Treatment of RET-altered cancers has been quite challenging since response rates to chemotherapy were relatively low." (PMID 37360768, 2023). "A group that has often been identified as a major contributor to fusions, as well as cancers driven by other mutations, is the RTKs, especially the FGFR and NTRK subfamilies, as well as RET and ALK." (PMID 37509339, 2023). "In both models, a positive response to the RET inhibitor pralsetinib was observed as demonstrated by the downregulation of the cancer markers, indicating that their expression is regulated by RETC634Y mutation." (PMID 38132167, 2023). "Other top pathways identified in SHH include signaling and loss of function of TGF-β receptor in cancer, SOS-mediated signaling, signal attenuation, and signaling in RET and advanced glycosylation end product receptor." (PMID 37035203, 2023). "Those drugs led to a paradigm shift in the treatment of RET-altered cancers, with higher response rates and more tolerable toxicity profile." (PMID 38118420, 2023). "Cancer cells with high SCN phenotype scores showed a strong dependency on RET kinase activity with a high correlation between RET and ZBTB7A dependencies in these cells." (PMID 37065756, 2023). "Little data are available on the efficacy of chemoimmunotherapy in patients with RET-altered cancers." (PMID 37627175, 2023). "Whereas activating RET mutations predominantly involve MTC, such alterationsthey have also been detected in other cancer populations." (PMID 37627175, 2023). "Recently, selpercatinib has received a tissue-agnostic FDA approval for all RET-fusion-positive cancers, and pralsetinib has shown pan-cancer activity as well." (PMID 38118420, 2023). "The RET oncogene encodes for an RTK, constitutive activation caused by fusions or mutations that lead to the development of cancer." (PMID 36768635, 2023). "First-line selpercatinib use is associated with improved outcomes compared to first-line comparator therapies for patients with advanced/metastatic RET-activated cancers." (PMID 38201566, 2023). "Utilizing SCN scores and gene dependency scores, we demonstrated that SCN-like cancer cell lines resemble NEPC cell lines in terms of RET expression and dependency." (PMID 37065756, 2023). "RET fusion proteins have been detected in more than 20 cancer types, with thyroid and lung adenocarcinomas being the most prevalent." (PMID 37375228, 2023). "This review will primarily focus on selpercatinib and its activity in RET fusion-positive cancers starting with NSCLC and expanding beyond that to tissue-agnostic activity." (PMID 37360768, 2023). "Other top pathways identified in SHH include signaling and loss of function of TGF-β receptor in cancer, SOS-mediated signaling, signal attenuation, signaling in RET, and advanced glycosylation end product receptor." (PMID 37035203, 2023). "Selective RET inhibitors, including selpercatinib and pralsetinib, have led to a paradigm change in treatment of RET-altered cancers." (PMID 38118420, 2023). "Outside of NSCLC and PTC, RET fusions have been identified in other cancer types at variable frequencies." (PMID 37627175, 2023).